IL6 (interleukin 6)
Diseases named in the same sentence as IL6 in open-access papers (continued):
Sharing a sentence is not in itself a finding about the gene and the disease.
breast cancer (continued). "Previous evidence indicates that Toll-like receptor 4 contributes to the development of paclitaxel resistance in advanced breast cancer cells by increasing the expression of pro-inflammatory cytokines such as IL-6 and IL-8, as well as the anti-apoptotic protein XIAP." (PMID 33324567, 2020). "To determine whether IL-6 exposure functionally enhanced the invasive capacity of breast cancer cells, we used a cell invasion chamber composed of Transwells and embedded with hydrogel." (PMID 33659239, 2020). "This indicates that breast cancer cells downregulate ATR in BSFs in an IL-6-dependent manner." (PMID 32414408, 2020). "Il-6 positively correlates with breast cancer progression and development of metastasis." (PMID 33297495, 2020). "Consequently, IL-6 induced the EMT process to various subtypes of breast cancer cells except for the stem cell populations." (PMID 33659239, 2020). "Additionally, it has been demonstrated that fibroblasts isolated from different sites of breast cancer growth, including the breast, lung and bone, enhance the invasiveness of ER+ breast cancer cells in an IL-6 dependent way." (PMID 32232008, 2020). "Therefore, we sought to investigate the possible implication of breast cancer cells in ATR downregulation in BSFs through IL-6 signaling." (PMID 32414408, 2020). "In addition, adipocyte-derived conditioned media induced phosphorylation of AKT and mTOR and upregulated the expression of target genes of the PI3K-AKT-mTOR pathway including IL6, IL1β, IL1α and TNFα in breast cancer cells." (PMID 32201525, 2020). "Interestingly, adipocytes and CAAs in breast cancer stroma have been shown to induce cancer cell EMT through soluble factors such as IL-6 and leptin, both of which activate Stat3 signaling and promote cancer cell migration and invasion." (PMID 32242230, 2020). "In addition to G-CSF, another two pro-inflammatory genes, IL-6 and IL-1β, also exhibited higher expression levels in breast cancer tissue-derived adipose." (PMID 32242230, 2020). "In addition, apigenin inhibited the growth of MDA-MB-231 breast cancer xenografts accompanied by reduced levels of IL-6, pSTAT3, pERK, PI3K, pAkt, and N-cadherin." (PMID 32521759, 2020). "Similarly, breast cancer-derived sEVs induce NFκB activation via TLR2 in macrophages resulting in upregulation of IL-6, TNF-α, G-CSF, and CCL2." (PMID 32015297, 2020). "OSM has also been shown to induce IL-6 in a STAT3-dependent manner in ER- breast cancer cells." (PMID 32023849, 2020). "Additionally, the shRNA targeting of RANKL in breast and prostate cancer, and shRNA targeting of IL-6 in breast cancer, resulted in smaller osteolytic lesions, reduced bone turnover, and reduced osteoclast numbers in inoculated mice." (PMID 32023849, 2020). "Therefore, targeting the IL-6/JAK/STAT3 pathway can be considered as an effective therapeutic approach for cancers associated with overexpression of IL-6, including breast cancer." (PMID 32847008, 2020). "However, serum samples collected immediately after an acute bout of exercise—which, as expected, exhibited a high concentration of adrenaline, noradrenaline, lactate and IL-6—reduced the viability of the breast cancer cell lines by approximately 9%." (PMID 33597950, 2020). "In metastatic cancer such as prostate and breast cancer, cancer cells in the bone marrow produce cytokines such as tumor necrosis factor α (TNFα), interleukin 6 (IL6), and vascular endothelial growth factor (VEGF) that can trigger recruitment and subsequent differentiation." (PMID 33086479, 2020). "Importantly, we firstly reported the inhibitive effects of Faecalibacterium prausnitzii for the growth of breast cancer cells through IL-6/STAT3 pathway." (PMID 32272885, 2020). "In breast cancer, adipocytes from the tumor microenvironment could produce IL-6, which then activates STAT3 in cancer cells and induces the EMT phenotype by increasing the expression of PLOD2, which is important for matrix remodeling." (PMID 33322216, 2020).
breast cancer (continued). "Studies by Kinder and colleagues report that metastatic MDA-MB-231 breast cancer cells increase the production of inflammatory cytokines such as IL-6, monocyte chemoattractant protein-1 (MCP-1), and IL-8 in both, human hFOB 1.19, and murine M3T3-E1 osteoblasts." (PMID 32232008, 2020). "Therefore, IL-6 can induce the EMT process on various subtypes of breast cancer cells, except the stem-like subtype, and also enhances the invasiveness of tumor cells." (PMID 33659239, 2020). "Similarly, an alternative approach to target cancer angiogenesis using an siRNA-based silencing approach was reported by Bharti and colleagues, who focused on IL-6/IL-6R and mitochondrial signaling in breast cancer." (PMID 33322132, 2020). "IL-6 is a crucial proinflammatory cytokine produced at the inflammation site and high IL-6 concentration in plasma and tissue may grant a worse prognosis to patients with breast cancer (BC)." (PMID 33126617, 2020). "c-Jun binds at the proximal IL6 promoter to promote IL-6 generation in breast cancer cells." (PMID 31527064, 2019). "Additionally, the blockade of IL-6 induced with TB-2-081 increased phosphorylation of the signal transducer and activator of transcription 3 (pSTAT3) in breast cancer cells and reduced osteolytic bone remodeling." (PMID 31847214, 2019). "Taken together, our data suggested that PIM1 might be a target for IL-6 induced breast cancer cell EMT and stemness." (PMID 30989585, 2019). "Interestingly, findings reported here showed a significant suppression of IL-6 in the breast cancer-bearing mice challenged with NDV (8-64HA) and a combination of NDV and tamoxifen (8-64HA) compared with cancer control group (CC)." (PMID 30947706, 2019). "Both OSM and IL-6 increase breast cancer metastatic potential in vitro as well as promote metastasis in vivo, suggesting that high levels of these cytokines may negatively affect patient survival." (PMID 31007849, 2019). "The synergistic upregulation of IL-6 secretion in response to OSM and IL-1β suggests that these cytokines may be using separate pathways to promote IL-6 in breast cancer cells." (PMID 31007849, 2019). "Interestingly, IL-6-induced stemness in breast cancer cells has been shown to occur by activating the expression of OCT4 gene via the janus kinase/signal transducer and activator of transcription protein 3 (JAK1/STAT3) pathway." (PMID 31450577, 2019). "Once an IL-6-induced EMT model in primary breast cancer cells was established, we investigated whether MTF is able to reverse EMT." (PMID 31337349, 2019). "In addition, IL-6 has proven protective effect against paclitaxel and doxorubicin in ERα-positive breast cancer, and also against trastuzumab in Her-2 positive tumors." (PMID 30927930, 2019). "Moreover, MTF overturned IL-6-stimulated cell proliferation and migration of cultured primary breast cancer cells." (PMID 31337349, 2019). "Hence, our data for the first time, indicated that PIM1 was a downstream target of IL-6 and critical for breast cancer cell EMT and stemness." (PMID 30989585, 2019). "Moreover, MCT-1 and IL-6 gene promotion was correlated in breast cancer patients with 3-year metastasis (r = 0.23, p = 0.008), 5-year metastasis (r = 0.26, p = 0.007) and bone metastasis (r = 0.39, p = 0.0002, n = 90) in the Bos dataset." (PMID 30885232, 2019). "Also, TGF-beta converted CD44− non-cancer stem cells (CSCs) into undifferentiated CD44+ CSCs in colorectal cancer, and IL-6 and IL-8 were important to maintain aggressive traits of breast cancer cells." (PMID 30989585, 2019). "IL-6 that is important in Th17 differentiation, as well as cancer-associated inflammation, was detected in oral squamous cell carcinoma and in vitro culture of KM22, a breast cancer cell line." (PMID 31024835, 2019).
breast cancer (continued). "Coculture of breast cancer cells with tumor tissue-derived MSCs (BC-MSCs) led to the development of cisplatin resistance; this process could be associated with the IL-6 secreted by BC-MSCs, which activates STAT3 signaling in breast cancer cells and promotes cell survival." (PMID 30927928, 2019). "The authors analyzed a panel of 34 cytokines, chemokines, and growth factors in the SWF of breast cancer patients and found, that the concentrations of IP-10, IL-6, G-CSF, osteoponin, MIP-1 alpha, MIP-1 beta, and MCP1-MCAF were higher in more aggressive tumors." (PMID 31861498, 2019). "A large body of evidence indicates that circulating inflammatory biomarkers, including interleukin (IL)-4, IL-6, IL-8, C-reactive protein (CRP), and tumor necrosis factor-α (TNF-α), may be associated with breast cancer risk." (PMID 31430979, 2019). "Breast cancer cell is known to produce numerous osteolytic factors including parathyroid hormone-related protein (PTHrP), IL-1, IL-6, IL-8, IL-11, vascular endothelial growth factor (VEGF), connective tissue growth factor (CTGF), matrix metallopeptidase 1 (MMP1), hepatocyte growth factor, etc12–16." (PMID 31040267, 2019). "In ovarian cancer cells, IL-6 and IL-8 activated estradiol-responsive genes, and reciprocal regulation between these signaling pathways was observed, similarly to our findings in breast cancer cells." (PMID 30736340, 2019). "However, in order to evaluate the main contributors involved in IL-6 expression during breast cancer bone metastases, numerous in vitro and in vivo studies analyzed tumor cells, bone cells, immune cells, and the organic bone matrix." (PMID 31847214, 2019). "overexpress STAT3K685R also inhibits IL-6-induced breast cancer cell migration about 40%." (PMID 31409371, 2019). "However, IL-6 released by breast cancer cells mediates “homing” of MSCs into primary tumor sites, and then interacts with its MSC receptor to induce MSC CXCL7 secretion." (PMID 30927930, 2019). "In the present study, we tested whether primary cultures of breast cancer epithelial cells develop EMT when exposed to IL-6, a well-known pro-inflammatory cytokine that promotes EMT in several cancers via the JAK-STAT3-SNAIL signaling pathway." (PMID 31337349, 2019). "Together, these results clearly demonstrate that breast cancer progression is associated with increased serum levels of both OSM and IL-6 and that the serum concentrations of these two cytokines correlate with each other, similar to the results with tumor expression levels of OSM and IL-6." (PMID 31007849, 2019). "Path analysis revealed that the serum CRP level, but not the serum IL-6 level, mediated the association between dietary magnesium intake and breast cancer risk." (PMID 30962499, 2019). "Based on these findings we speculate that IL-6/STAT3 signalling pathway is a key pathway by which adipocytes drive breast cancer migration and invasion." (PMID 31383893, 2019). "Here, IL-6 has an important role in acquired breast cancer chemo-resistance through its secretion by MSC which promotes great impact on the stimulation of ERα-positive breast cancer cell proliferation." (PMID 30927930, 2019). "Importantly, inhibition of p-STAT3 was accompanied by a reduction in IL-6 secretion, hence depriving breast cancer cells of this critical growth-promoting factor." (PMID 31491838, 2019). "Different cytokines such as transforming growth factors like beta (TGF-β), interleukin 1 (IL-1), IL-6, and IL-17 could stimulate breast cancer cell proliferation and/or invasion." (PMID 30642295, 2019). "Finally, we analyzed the association between IL-6, PTGER2, and PTGER4 overexpression and breast cancer subtype; hormone receptor status; and distant metastasis-free or overall survival." (PMID 31014367, 2019). "Moreover, breast cancer-derived exosomes are capable of inducing IL-6 secretion and a pro-tumoral phenotype (IL-6, IL-10, CCL2 production) in macrophages, partially via gp130/STAT3 signaling." (PMID 31480382, 2019).
breast cancer (continued). "Since the role of IL-6 in cancer progression has been reported previously, it has also been investigated in experimental cancer models for various types of cancer, including oral, lung, ovarian, and breast cancers." (PMID 30927911, 2019). "Anti-apoptotic molecules such as IL-6, IL-10 and TNFα are implicated in drug resistance in non-Hodgkin’s lymphoma, breast cancer, and glioma." (PMID 31395078, 2019). "Also, the neutrophils physically clustered with circulating 4T1 breast cancer cells support the cancer cell cycle progression, secreting IL-6 and IL-1β, and promote metastasis of cancer cells." (PMID 31474975, 2019). "This prompted us to investigate whether OSM signals mammary tumor cells to increase IL-6 expression in vivo." (PMID 31007849, 2019). "Since MTF interfered with IL-6-induced EMT of primary breast cancer cells, we then analyzed whether MTF had an effect on cell proliferation and migration." (PMID 31337349, 2019). "To address the possibility that SASP (high secretions of IL-6 and IL-8) from senescent cells affects carcinoma cells migration, we examined the consequences of treatments with conditioned medium (CM) on the motogenic response of human breast cancers." (PMID 30871042, 2019). "Our study provides evidence that human-adipocyte CM can induce EMT in breast cancer cells through the IL-6/STAT3 signalling pathway, perturbation of IL-6/STAT3 signalling with niclosamide inhibit STAT3 phosphorylation and reverse adipocyte-induced EMT in breast cancer cells." (PMID 31383893, 2019). "Thus, niclosamide is a potent inhibitor of adipocyte-induced EMT in breast cancer cell by inhibiting the IL-6/STAT3 axis in breast cancer cells." (PMID 31383893, 2019). "Furthermore, OSM, IL-6, and IL-1β expression levels in breast cancer tissue are all strongly correlated with each other." (PMID 31007849, 2019). "The rs4648090 polymorphism has also been related to decreased risk of breast cancer among women with European ancestry and to interact with other SNPs in the IFNG, IRF2, IL6, and NFKB1 genes to affect risk of colon cancer, and with IRF6 and NFKB1 genes for risk of rectal cancer." (PMID 30781516, 2019). "We also assessed the expression of Ifn-γ, Il-6 and Il-10 in mammary tumors." (PMID 30640711, 2019). "Moreover, these molecular regulatory circuits have shown that mammary tumor cells are able to survive through autocrine IL-6 production, and independently of the paracrine release of IL-6 by the tumor stromal cells." (PMID 31557902, 2019). "We determined whether IL-6 induced PIM1 in breast cancer cell lines, leading to the increased expression of PIM1." (PMID 30989585, 2019). "The Stat3/PAK1 complex is essential for IL-6 gene expression and breast cancer stemness." (PMID 31658701, 2019). "Interleukin-6 (IL-6) has been demonstrated to be a critical factor for breast cancer malignancy." (PMID 30989585, 2019). "siRNA knockdown of STAT3 blocked macrophage-induced expression of breast cancer proliferative genes cyclin D1 and c-Myc, and of cytokines IL-6, CCL5, and MCP-1, demonstrating the essential role of STAT3 expression in conditioned macrophage-induced alteration of gene expression." (PMID 30736340, 2019). "However, there is little evidence from observational studies investigating the effect of IL-6 level on breast cancer risk." (PMID 30962499, 2019). "Results presented here demonstrate that NF-κB- and IL-6-dependent signaling pathways play essential roles in macrophage-mediated induction of endocrine resistance in ER+ breast cancer cells, and the consequent ability of these cells to proliferate in estradiol-independent manner." (PMID 30736340, 2019). "We examined whether blocking IL-6 expression may inhibit the growth and metastasis of breast cancer in vivo using a xenograft mouse model." (PMID 31252615, 2019). "Therefore, IL-6 promotes the invasion, metastasis, and angiogenesis of breast cancer mainly by activating JAK/STAT3 signaling pathway." (PMID 31500658, 2019).
breast cancer (continued). "Therefore, it is logical to think that a reduction in pain reported by breast cancer survivors can be a predictor of a reduction in IL-6 concentration such as that observed in our results." (PMID 31414667, 2019). "The role of IL-6 in breast cancer growth and progression is complicated." (PMID 31014367, 2019). "However, the molecular mechanisms by which IL-6 induce breast cancer cells epithelial–mesenchymal-transition (EMT) and stemness remain elusive." (PMID 30989585, 2019). "In breast cancer, IL6 was able to activate dormant cancer cells, a mechanism that could also be relevant for sarcoma recurrence after local resection." (PMID 31906053, 2019). "In addition, IL-6 was found to pathologically regulate various types of cancer, including colorectal cancer, lung cancer and breast cancer." (PMID 30947706, 2019). "Importantly, these findings also indicate that even when ER+ breast cancer cells, such as T47D cells, are unable to produce IL-6 in response to OSM or IL-1β, they can still undergo invasive characteristics independently of IL-6." (PMID 31007849, 2019). "Moreover, available evidence indicates that both IL-6 and IL-11 cytokines are produced constitutively at equivalent levels by breast cancer cells." (PMID 31491838, 2019). "The boosting concentrations of IL-6 during the establishment of GD pathogenesis, might act as host factors that can support breast carcinoma." (PMID 30881358, 2019). "Moreover, IL-6 secreted by adipose tissue binds to IL-6 receptor on breast cancer cells and activates the Janus family of kinases that phosphorylates signal transducer and activator of transcription-3 (STAT-3)." (PMID 30619088, 2018). "Thus, SOCS3 suppression accelerated the IL-6-mediated growth and metastasis of mammary carcinoma via affecting myeloid differentiation in breast cancer." (PMID 30083161, 2018). "ROS-activated NF-κB mediates the release of IL-6 in GC, breast cancer, glioma, and HNSCC." (PMID 29770167, 2018). "Interestingly, expression levels of IL8 and IL6 have been shown to be inversely correlated to the estrogen receptor status, with high IL8 and IL6 expression in ER− breast cancer cell lines with high invasive potential." (PMID 29930291, 2018). "However, studies on emotions and IL-6 in breast cancer patients are rare, and data have been equivocal." (PMID 30546293, 2018). "Multiple studies have established an immune-modulatory role for miR-146b, including suppression of IL-6 allowing p16-dependent tumorigenesis in breast cancer, as well as suppression of multiple other pro-inflammatory cytokines and chemokines such as TNF-alpha, IL-8, and IL-10." (PMID 30018734, 2018). "Treatment with a murine IL-6 blocking antibody or depletion of OBR abrogated both the expression of PLOD2 and adipocyte-stimulated metastasis, indicating that PLOD2 plays an important role in mediating breast cancer metastasis via adipocyte-derived IL-6 and leptin." (PMID 30563531, 2018). "Importantly, presence of CAAs expressing IL-6 was confirmed ex vivo using primary breast cancer samples." (PMID 30356678, 2018). "Finally, we analyzed the effect of RANTES and IL6 overexpression on tumor growth of breast cancer cells in vivo." (PMID 29707128, 2018). "Therefore, our results clearly suggest that adipocyte-derived IL-6 and leptin promote the invasive phenotype of breast cancer cells via upregulation of PLOD2 both in vitro and in vivo." (PMID 30563531, 2018). "Interestingly, co-culture of adipocytes and breast cancer cells resulted in a drastic increase of murine IL-6 levels." (PMID 29930291, 2018). "Furthermore, breast cancer cells cocultured with adipocytes or treated with either IL-6 or leptin displayed increased PLOD2 expression and activated JAK/STAT3 and AKT signaling pathways." (PMID 30563531, 2018). "TGFB1, TNF, IL1B and IL6 are inhibited by ligand-bound AhR in ERα-positive breast cancer cells." (PMID 29320557, 2018).